CCK (cholecystokinin)
Description:
This peptide hormone induces gall bladder contraction and the release of pancreatic enzymes in the gut. Its function in the brain is not clear. Binding to CCK-A receptors stimulates amylase release from the pancreas, binding to CCK-B receptors stimulates gastric acid secretion.
Tractability: Small molecule: a structure with a bound ligand is known. Antibody: UniProt places it where antibodies can reach, with high confidence; its Gene Ontology location is reachable by antibodies, with high confidence; UniProt predicts a signal peptide or a membrane-spanning region.
Target class: Secreted protein
Safety:
Unwanted effects reported when the protein is acted on. In parentheses: how it was acted on, where the effect was seen, and who reports it.
Increased, Pancreatic acinar tumors (serum; source: AOP-Wiki)
Gene: Protein-coding gene on chromosome 3 (42,257,823 to 42,266,185, reverse strand). Ensembl gene ENSG00000187094.
Subcellular location: Secreted
Pathways (Reactome):
Signal Transduction: G alpha (q) signalling events; Peptide ligand-binding receptors
Gene Ontology:
Molecular function: peptide hormone receptor binding; protein binding; hormone activity; neuropeptide hormone activity; receptor ligand activity
Biological process: axonogenesis; digestion; eating behavior; neuron migration; signal transduction; cholecystokinin signaling pathway
Cellular component: extracellular region; axon
Genetic constraint (gnomAD): Loss-of-function variants: 12 observed, 11.6 expected, observed/expected ratio (o/e) 1.03, 90% interval 0.66 to 1.65. The upper end of that interval is the gene's LOEUF score, 1.65, which puts it in group 6 of 6, group 1 being the genes least tolerant of losing a copy. Missense variants: 137 observed, 166.5 expected, observed/expected ratio (o/e) 0.82, 90% interval 0.71 to 0.95. Synonymous variants: 83 observed, 76.14 expected, observed/expected ratio (o/e) 1.09, 90% interval 0.91 to 1.31.
Homologues: Orthologues: chimpanzee CCK (99% identical), macaque CCK (96% identical), dog CCK (87% identical), pig CCK (83% identical), mouse Cck (81% identical), guinea pig CCK (74% identical), rat Cck (50% identical), zebrafish ccka (43% identical), tropical clawed frog pgq (19% identical).
Diseases named in the same sentence as CCK in open-access papers:
CCK is named in the same sentence as 231 diseases in open-access papers, as found by Europe PMC text mining. Sharing a sentence is not in itself a finding about the gene and the disease. The quoted sentences say what the papers report.
Obesity (144 papers, 2007 to 2026). Accumulation of substantial excess body fat. "Here, we show that β cell expression of the peptide hormone cholecystokinin (CCK) is necessary and sufficient for obesity-associated PDAC progression in mice and that CCK expression - rather than insulin - correlates strongly with enhanced tumorigenesis." (PMID 41760660, 2026). "L. acidophilus H-68, identified in the normal-weight children, demonstrates anti-obesity potential, which was associated with stimulating CCK secretion and producing BSH." (PMID 38731751, 2024). "Some studies have shown that PCOS is associated with abnormal regulation of cholecystokinin and ghrelin hormones, that control appetite, and causes obesity." (PMID 38463925, 2024). "We also found that CCK is elevated in the lungs of mouse models of obesity-associated asthma, which implied that CCK/CCKAR mediates AHR in the obese." (PMID 36599824, 2023). "Our present study reveals that CCKAR mediates CCK-induced contraction of ASM cells and that CCK/CCKAR signaling is a mechanism underlying obesity-induced AHR in mice." (PMID 36599824, 2023). "Our results support a model in which elevated CCK level associated with obesity increases CCKAR signaling in the lung to constrict ASM cells to drive bronchoconstriction and AHR." (PMID 36599824, 2023). "A recent report also described a novel and intriguing role of cholecystokinin in obesity-associated PDAC." (PMID 37373094, 2023). "Diets rich in long-chain saturated fatty acids lead to the overexpression of CCK which alongside obesity, is a significant risk factor for pancreatic cancer and elevated CCK levels are also associated with the development of pancreatic metastases in mice." (PMID 34572888, 2021). "Defects in CCK signalling have been reported to contribute to obesity, since genetic mutations in CCK1 receptor result in increased meal size and food intake." (PMID 34072172, 2021). "One of the possible explanations for the association between migraine and obesity is CCK secretion in response to high fat diets as intra-duodenal free fatty acids stimulate CCK secretion." (PMID 32054443, 2020). "This is significant as a recent report described a novel and intriguing role of CCK in obesity-associated PDAC." (PMID 32709161, 2020). "Intriguingly, elevated β-cell expression of CCK is mediated by obesity-associated activation of islet macrophages." (PMID 32709161, 2020). "CPE (carboxypeptidase E), an obesity susceptibility gene, has been shown to be responsible for the processing of pro-CCK into its bioactive forms." (PMID 32690984, 2020). "Further investigation is needed in order to determine if the HbA1c correlated responsiveness to exogenous gastrin is linked to this increase in CCK production within the islets during obesity which is known to correlate with increased HbA1c1." (PMID 31430329, 2019). "However, leptin and insulin resistance caused by obesity result in reduced efficacy of satiety hormones like peptide YY and cholecystokinin over time, ultimately leading to decreased fullness." (PMID 40443725, 2025). "The present research focused on evaluating the in vivo effects of NAR on plasma CCK and ghrelin levels, two important peptide hormones involved in the hunger/satiety pathway, as well as its effects on metabolic parameters associated with obesity in a rat model of diet-induced obesity." (PMID 39997735, 2025). "Here we report that cholecystokinin—a metabolic hormone best known for its role in signaling satiation and fat metabolism—is increased in the lungs of obese mice and that pharmacological blockade of cholecystokinin A receptor signaling reduces obesity-associated airway hyperresponsiveness." (PMID 36599824, 2023). "In addition to CCK, ghrelin is also known to regulate food intake via AgRP neurons and obesity is thought to cause ghrelin resistance in AgRP neurons as measured by Fos staining and ex vivo recordings." (PMID 32720646, 2020).
Obesity (continued). "Since alterations in gastrointestinal motor functions in obesity may present useful targets for preventing and treating metabolic disorders, the management of gastric emptying by hormones, such as CCK, may be a good strategy to reduce the impacts associated with these metabolic diseases." (PMID 30734596, 2019). "In individuals with obesity, there appears to be resistance of vagal neurons to CCK, leading to a diminished anorexigenic effect and perhaps impaired CCK secretion." (PMID 41575482, 2026). "The protective effect of exercise is thought to stem from its ability to guard against central and general obesity, as well as its role in increasing plasma cholecystokinin and vagal tone, which together stimulate gallbladder contraction and emptying." (PMID 40129666, 2025). "The obesity studies showed that the plasma CCK concentrations both in the fasting state and after intake of mixed meals are the same in lean and obese people." (PMID 40557463, 2025). "For example, the effects of intraduodenal oleic acid to stimulate CCK, PYY, and pyloric pressures are diminished in individuals with obesity, compared with those with normal weight, associated with greater energy intake." (PMID 39785828, 2025). "In obesity, vagal neurons become less responsive to CCK, leading to reduced satiety signaling and altered energy balance." (PMID 41150735, 2025). "Cholecystokinin (CCK), an appetite-regulating hormone, is commonly used to suppress appetite in obesity therapy." (PMID 40807276, 2025). "Hyperphagia in BBS appears to result from multifactorial disruptions, whereby intrinsic defects in CCK signaling pathways and receptor function further exaggerated obesity-related resistance to satiety signals." (PMID 40233116, 2025). "In conclusion, the changes in CCK secretion and effects found in obesity and eating disorders are modest and as such hardly decisive." (PMID 40557463, 2025). "This CCK-mediated mechanism contributes to its anti-obesity effects by promoting satiety and suppressing appetite." (PMID 41031363, 2025). "Obesity induces ectopic expression of cholecystokinin in pancreatic β-cells, which can independently drive KRAS-mediated tumorigenesis." (PMID 40732935, 2025). "A part of the anti-obesity potential of L. acidophilus H-68 comes from its ability to promote cholecystokinin (CCK) secretion." (PMID 38731751, 2024). "Ghrelin, peptide YY (PYY), cholecystokinin (CCK), and amylin are crucial in appetite regulation offering promising targets for pharmacological interventions in obesity treatment using both peptide‐based and small molecule‐based pharmaceuticals." (PMID 39016695, 2024). "Ghrelin, PYY, CCK, and amylin have promising prospects for novel pharmaceutical interventions in appetite regulation and obesity treatment." (PMID 39016695, 2024). "These satiation and satiety signals are known to be compromised, i.e., blunted, in HF feeding and obesity as a result of decreased sensitivity to CCK." (PMID 38853960, 2024). "In pursuing more effective therapies for obesity and diabetes, CCK analog NN9056 has emerged as a promising candidate, especially when combined with the GLP-1R agonist semaglutide." (PMID 39529694, 2024). "In obesity, the satiety effect of CCK seems to be weakened, and its plasma level is significantly increased, both in obese patients and in animal models of disease." (PMID 38542187, 2024). "We have not identified any ongoing human trials investigating the impact of CCK as a potential treatment for obesity." (PMID 39016695, 2024). "We and others have found that prolonged obesity in Lepob/ob mice stimulated increasing β cell expression of the peptide hormone cholecystokinin (CCK)." (PMID 37648285, 2023). "Obesity accelerated PDAC development through changes in the local pancreatic microenvironment driven by increased pancreatic islet (β-cells)-secreted cholecystokinin acting locally on pancreatic acinar cells to accelerate ADM formation." (PMID 37373094, 2023).
Obesity (continued). "A CCK agonist has been demonstrated to achieve anti-obesity effects with remarkable efficacy, reducing weight and appetite signals, but also acting like a GLP-1 potentiator when used as adjunct therapy." (PMID 37753211, 2023). "A recent study found abnormal beta cell expression of the peptide hormone cholecystokinin (CCK) in response to obesity and demonstrated that it promotes oncogenic Kras-driven pancreatic ductal tumorigenesis." (PMID 37445352, 2023). "As a result, enzymatically stable, physiologically active CCK peptide analogs with therapeutic potential in obesity and T2DM have been created." (PMID 36790719, 2023). "Together, our results reveal an unexpected role for cholecystokinin in the lung and support the repurposing of cholecystokinin A receptor antagonists as a potential therapy for asthma patients with obesity." (PMID 36599824, 2023). "Cholecystokinin (CCK) from I cells promotes satiety and reduces food intake by suppressing hunger; however, the role of CCK in obesity remains controversial." (PMID 37240181, 2023). "Strikingly, we confirmed the dysregulation of Cck using a targeted quantitative polymerase chain reaction approach between tested groups with significantly reduced CCK gene expression due to LR application in HFD-induced obesity." (PMID 37881580, 2023). "The reverse has also been shown to be true when feeding healthy diets, such as a high-protein diet, which led to increased vagal sensitivity to CCK in mice with diet-induced obesity." (PMID 37571301, 2023). "In Pdx1-Kras–expressing ob/ob mice, obesity led to aberrant cholecystokinin (CCK) expression in islet cells, which accelerated Kras-driven pancreatic ductal tumorigenesis." (PMID 37338995, 2023). "Its potential action in the CNS-mediated control of obesity-associated AHR, if at all, would likely have to be through brainstem-derived CCK." (PMID 36599824, 2023). "The principal finding is that Ramadan fasting has a beneficial effect on gut hormone levels for leptin, glucagon-like peptide-1 (GLP-1), peptide YY (PYY), and cholecystokinin (CCK) in males with obesity." (PMID 37139278, 2023). "Further exploration of these differences will open up the possibility of CCK-targeted enteroendocrine therapeutics that can promote satiety and reduce the burden of obesity." (PMID 37240181, 2023). "Taken together, these findings suggest that diet-induced obesity through the introduction of HFD impairs CCK signaling through gut microbiota dependent mechanisms, which can alter feeding patterns leading to hyperphagia and obesity." (PMID 37571301, 2023). "Our data using obese mouse models further demonstrate that antagonizing CCK/CCKAR in the lung attenuates obesity-induced AHR." (PMID 36599824, 2023). "Hormones that control hunger, satiety, obesity, glucose, and maintain weight include leptin, ghrelin, cholecystokinin (CCK), oxyntomodulin (OXM), glucagon-like receptor-1 (GLP-1), insulin-like peptide-5 (INSLP-5), and peptide YY (PYY)." (PMID 36790719, 2023). "Here, the authors show that antagonizing cholecystokinin and its receptor, CCKAR, in the lung attenuates obesity-associated airway hyperresponsiveness in mice." (PMID 36599824, 2023). "Antagonizing such elevated CCK/CCKAR signaling in the ASM blocks obesity-induced AHR and thus presents a completely new way to treat asthma in patients with obesity." (PMID 36599824, 2023). "High-fat diet-induced obesity is shown to promote dysbiosis leading to a state of systemic inflammation that induces hyperphagia by altering vagally mediated satiety via CCK." (PMID 37571301, 2023). "Leptin-resistant diet-induced obesity (DIO) rats demonstrated decreased CCK sensitivity on vagal afferent nerves, which attenuates the effect of CCK on satiety." (PMID 36834794, 2023). "A previous study showed that Igfbp6 was expressed at lower levels in obesity and was positively correlated with leptin, glucagon-like peptide 1 and cholecystokinin." (PMID 36209126, 2022).
Obesity (continued). "CCK-resistance in obesity is evident, making obese individuals less sensitive to CCK’s satiety effect." (PMID 35334929, 2022). "Basal concentrations and responses to an oral glucose tolerance test of glucagon, GLP-1, GIP, CCK, and gastrin at baseline and after matched ~6% weight loss by a CD or a CRHP diet in individuals with T2D and overweight or obesity." (PMID 36061897, 2022). "The focus of this review is the role played by one specific gastrointestinal hormone, cholecystokinin, in the physiology of nutrition and potentially for therapeutic approaches to prevent and manage obesity." (PMID 34149622, 2021). "They found that slow ES resulted in lower energy intake and postprandial ghrelin concentration along with higher postprandial GLP-1 and cholecystokinin concentrations in both lean and subjects with obesity compared to fast ES." (PMID 34952593, 2021). "When the prevalence and adverse implications of obesity began to be appreciated, cholecystokinin agonists that are active at CCK1R were widely sought as possible therapeutic tools." (PMID 34149622, 2021). "In particular, CCK-based regulation of energy intake and pancreatic endocrine islet function make the hormone a potentially attractive therapeutic agent for obesity and diabetes." (PMID 34054734, 2021). "One feature of diet-induced obesity (DIO) in humans has reduced sensitivity to CCK, and vagal afferent neurons phenotypic flexibility is lost in DIO." (PMID 34675965, 2021). "Together, these data highlight the effectiveness of sustained dual GLP-1 and CCK1 receptor activation by [Lys12Pal]Ex-4/CCK for the treatment of obesity-related diabetes." (PMID 34054734, 2021). "Obesity is a multifaceted disease where intestinal hormones such as cholecystokinin (CCK), glucagon-like peptide 1 (GLP-1), and peptide YY (PYY), produced by enteroendocrine cells (EECs), have a pivotal role as signaling systems." (PMID 33669189, 2021). "CCK represents an interesting target for the development of obesity-diabetes therapy, as shown by in vitro studies and animal models based on the administration of CCK peptide analogues." (PMID 33668627, 2021). "This study investigated the effects of RIF on gut hormones (leptin, ghrelin, GLP-1, PYY, and CCK) in males with obesity in Tunisia." (PMID 32756479, 2020). "Obesity is accompanied by altered secretions of leptin, ghrelin, GLP-1, PYY, and CCK, which are in turn associated with accelerated weight gain." (PMID 32756479, 2020). "We studied the effects of Ramadan intermittent fasting (RIF) on gut hormones (leptin, glucagon-like peptide-1 (GLP-1), peptide YY (PYY), cholecystokinin (CCK), and ghrelin) in males with obesity." (PMID 32756479, 2020). "Postprandial concentrations of active glucagon-like peptide 1, total peptide YY, and cholecystokinin were lower in individuals with obesity at all time points compared with controls." (PMID 32301981, 2020). "CCK is another peptide hormone commonly expressed in neuroendocrine cells in the gut, yet rodent pancreatic islets also express and secrete CCK under conditions of metabolic stress such as obesity and insulin resistance." (PMID 32071395, 2020). "Ingestion of fat is communicated to AgRP neurons in part through CCK and, consistent with this, we found that obesity also desensitizes AgRP neurons to peripheral CCK." (PMID 32720646, 2020). "Some diet-induced obesity, such as that induced by a hyperlipidic diet, alter sensitivity to CCK, whereas, in some animal models, the low sensitivity to CCK is a condition that preceds obesity." (PMID 30734596, 2019). "In diet-induced obesity in Sprague–Dawley rats, weight reduction was observed only in 23 days after exogenous CCK-8 was received." (PMID 29322840, 2018). "There is evidence that individuals and animals with obesity do not show the same sensitivity to the satietogenic effects of cholecystokinin (CCK) when compared to eutrophic, and the resistance to leptin is increased especially in the state of obesity." (PMID 29322840, 2018).